TAGLN (transgelin)
Diseases named in the same sentence as TAGLN in open-access papers (continued):
Sharing a sentence is not in itself a finding about the gene and the disease.
mucinous ovarian carcinomas (1 paper, 2022). An invasive malignant neoplasm that arises from the ovary and is characterized by the presence of malignant epithelial cells that contain intracytoplasmic mucin and may resemble the epithelial cells of the endocervix or gastrointestinal tract. "This analysis of a large series of mucinous ovarian carcinomas has identified two potential prognostic biomarkers in THBS2 and TAGLN, which could have clinical utility and deserve further investigation." (PMID 36222710, 2022).
myocardial infarction (1 paper, 2021). Gross necrosis of the myocardium, as a result of interruption of the blood supply to the area, as in coronary thrombosis. "Our results may provide a certain reference value for the function of transgelin protein to reduce the area of myocardial infarction." (PMID 34173041, 2021).
myocardial ischemia (1 paper, 2022). A disorder of cardiac function caused by insufficient blood flow to the muscle tissue of the heart. "Similarly, the transgelin, acting via the transgelin–actin complex and modulating the reorganisation of the actin cytoskeleton, is known to participate in the regulation of the blood flows of coronary arteries, and thus is a promising therapeutic target for the treatment of myocardial ischemia." (PMID 35054835, 2022).
nephropathic cystinosis (1 paper, 2024). An autosomal recessive condition caused by mutation(s) in the CTNS gene, encoding cystinosin. "TAGLN has low renal tubule expression under normal conditions, however, mouse models used to investigate nephropathic cystinosis revealed the upregulation of tubular TAGLN and increased O2- was present in tubular swan neck lesions leading to apoptosis." (PMID 39480826, 2024).
neuroblastoma (1 paper, 2021). Neuroblastoma (NB) is the most common solid, extracranial childhood tumor. "Several studies indicate the colocalization of all three transgelin members with F-actin in certain cell types, namely, TAGLN in fibroblasts, TAGLN2 in T-cell immunological synapse, and TAGLN3 in neuroblastoma cells." (PMID 34322481, 2021).
pancreatic ductal adenocarcinoma (1 paper, 2023). An infiltrating adenocarcinoma that arises from the epithelial cells of the pancreas. "Similarly, TAGLN was reported as a specific marker of CAFs in the mesenchymal stroma of pancreatic ductal adenocarcinoma." (PMID 36990991, 2023).
PN tumor (1 paper, 2014). "In patient P8, we compared the PN tumor from the first surgery and the MPNST tumor from the second surgery (a 2-year interval) and found significantly higher transgelin expression in the MPNST tumor than in the PN tumor." (PMID 25109740, 2014).
polyp (1 paper, 2023). A usually exophytic mass attached to the underlying tissue by a broad base or a thin stalk. "We found that TAGLN expression was significantly increased in high-risk polyp tissues, yet a significant decrease in expression was observed in cancerous tissue compared to healthy and adjacent healthy tissue." (PMID 37365287, 2023). "In conclusion, our study identified an association between the increased expression of CDC42, TAGLN, and GSN in high-risk polyps, suggesting a potential role in polyp malignancy." (PMID 37365287, 2023). "This implies that higher TAGLN expression may contribute to polyp malignancy, but its role in cancer progression is not straightforward." (PMID 37365287, 2023).
pulmonary diseases (1 paper, 2024). "Interestingly, transgelin expression disorder is associated with a serious of pulmonary diseases." (PMID 39676863, 2024). "Transgelin is a central actin-binding protein of the calponin family and involved in the process of multiple pulmonary diseases." (PMID 39676863, 2024).
renal fibrosis (1 paper, 2013). A final common manifestation of a wide variety of chronic kidney diseases characterized by glomerulosclerosis and tubulointerstitial fibrosis. "Microarray analysis and proteomic analysis have provided evidence for the up-regulation of transgelin in animal models of renal fibrosis." (PMID 23840546, 2013). "And third, we compare transgelin up-regulation in another animal model of renal fibrosis, induced by elevated blood pressure." (PMID 23840546, 2013). "Therefore, our data suggest that transgelin is up-regulated in the obstructive nephropathy and consequently could be used as a future novel marker for renal fibrosis." (PMID 23840546, 2013). "In addition, transgelin expression in periglomerular fibroblasts was absent in renal fibrosis developed in a hypertensive model, compared to the UUO model." (PMID 23840546, 2013).
Renal insufficiency (1 paper, 2024). A reduction in the level of performance of the kidneys in areas of function comprising the concentration of urine, removal of wastes, the maintenance of electrolyte balance, homeostasis of blood pressure, and calcium metabolism. "U IGFBP-7/creatinine ratio, U TIMP2/creatinine ratio, and serum transgelin levels were higher in patients with MM than healthy controls, and predicted renal insufficiency in MM." (PMID 38708150, 2024). "ROC curve analysis demonstrated that U IGFBP-7/creatinine ratio, U TIMP2/creatinine ratio, and serum transgelin had predictive value for renal insufficiency (eGFR < 60mL/min/1.73 m2)." (PMID 38708150, 2024).
skin aging (1 paper, 2023). The gradual irreversible changes in structure of skin that occur as a result of the passage of time.. "The overexpression vector of TAGLN and the corresponding siRNA were constructed, and efficiency validation was carried out to further explore the role of TAGLN in skin aging." (PMID 37149635, 2023). "However, few studies have investigated whether TAGLN can regulate UV-induced skin aging and whether a relationship exists between TAGLN and ZEB1." (PMID 37149635, 2023).
systemic sclerosis (1 paper, 2024). A chronic disorder, possibly autoimmune, marked by excessive production of collagen which results in hardening and thickening of body tissues. "The same is true in skin fibroblasts from patients diagnosed with systemic sclerosis and when they compared TAGLN expression between control and UV-irradiated skin fibroblasts." (PMID 39595975, 2024).
thrombosis (1 paper, 2022). "Staining with the VSMCs differentiation marker TAGLN was further performed, revealing that αSMA and TAGLN double‐positive VSMCs located at calcium deposits area also expressed Runx2, which suggested that VSMCs were involved in the calcification process of the venous wall after thrombosis." (PMID 35808901, 2022).
tumor (123 papers, 2007 to 2026). "Transgelin is associated not only with tumor genesis, but also with tumor invasion and metastasis potential." (PMID 34552870, 2021). "Transgelin was the second top up-regulated protein, and it was the only one with cytosol localization and a well-known association with tumor biology." (PMID 34572331, 2021). "TAGLN is implicated in cancer development and upregulated in stromal cells of lymph node positive breast cancer, but it is also reported to be a tumor suppressor, especially in liver cancers." (PMID 34001947, 2021). "Previous data on association of TAGLN with metastatic states of other tumor types are also controversial." (PMID 26421063, 2015). "Further studies are required to elucidate how transgelin upregulation in these cells is implicated in tumor progression in NF1." (PMID 25109740, 2014). "Elevated stromal TAGLN was associated with lymphatic metastasis and enhanced fibroblast activation and motility, which was mediated in part by NF-κB pathway activation and IL-6 secretion, thereby fostering a pro-inflammatory, tumor-promoting microenvironment." (PMID 40940809, 2025). "This higher expression of TAGLN observed in tumor-associated FIBs suggests that the gene may be related to cell immortalization and stemness." (PMID 39595975, 2024). "Although there is debate over whether or not transgelin plays a role in cancer development, many studies have demonstrated that elevated transgelin levels are associated with aggressive tumor behavior, advanced stage of the disease, and poor prognosis." (PMID 35409206, 2022). "However, when the patients were grouped for tumor grades, higher expression of TAGLN was associated with increased OS and RFS probabilities in patients with grade 1 and 2 tumors." (PMID 26421063, 2015). "The methylation profile of the TAGLN gene may be another biomarker that is useful for decision making with regard to the tumor progression of NF1-associated tumors." (PMID 25109740, 2014). "Furthermore, TAGLN is implicated in extracellular matrix disintegration and angiogenesis in smooth muscle development into stem cells and embryonic blood vessels, contributing to tumor cell invasion and angiogenesis." (PMID 35665757, 2022). "TAGLN also known as SM22α, is a smooth muscle marker and a tumor suppressor, a member of the calponin family of actin-binding proteins." (PMID 41146907, 2025). "TAGLN expression in myCAFs supports their activated, contractile phenotype and contributes to tumor progression." (PMID 40940809, 2025). "At the same time, TAGLN knockdown reduced tumor cell proliferation, migration, and EMT phenotypes in vitro and suppressed tumor growth in vivo." (PMID 40940809, 2025). "Tumour samples were obtained from PNFs and MPNSTs from eight NF1 patients to investigate the epigenetic regulation of the TAGLN gene, which encodes transgelin, an actin-associated protein." (PMID 40843672, 2025). "Genes with higher expression in the Normal tissue adjacent to neoplasm group included these markers as well as TAGLN and C11orf96." (PMID 40616092, 2025). "Four primary cell populations were first identified using canonical cell markers: WT tumor cells (WT1, NCAM1, SIX1, SIX2, PAX2), cancer-associated fibroblasts (CAFs) (ACTA2, TAGLN, COL1A1, PDGFRB), endothelial cells (PECAM1, CLDN5, ENG, VWF) and immune cells." (PMID 40098972, 2025). "In contrast to previous reports that TAGLN serves as a suppressor during tumorigenesis initiation in other cancers, TAGLN acts as a functional marker for tumor stemness in GBM." (PMID 38087889, 2024). "To characterize the nature of the RGS5+ cluster further, we stained tumor sections for Transgelin (TAGLN), which is a prominently expressed gene in this cluster." (PMID 39516494, 2024). "As valproate has been considered an HDAC2 inhibitor, we investigated the role of TAGLN in tumor cell response by rescuing treatment effects with TAGLN overexpression (TAGLN‐OE) in GSCs." (PMID 38087889, 2024).
tumor (continued). "Like transforming growth factor‐β (TGF‐β), which induces TAGLN, TAGLN serves context‐specific roles in cancer with both tumor‐suppressive and oncogenic functions in select cancer types." (PMID 38087889, 2024). "Transgelin is a protein involved in cytoskeletal organization and cell motility, the alteration of which can affect tumor cell migration." (PMID 39336170, 2024). "TAGLN is expressed at high levels in colorectal cancer and ovarian cancer, contributing to tumor infiltration and migration at advanced tumor stages." (PMID 38087889, 2024). "Analysis of tumor‐bearing brains revealed that targeting TAGLN expression in GSCs reduced the expression levels of TAGLN, the proliferation marker Ki67, and the GSC marker SOX2, but increased levels of the GFAP differentiation marker and Cleaved Caspase3." (PMID 38087889, 2024). "CAFs can also secrete numerous cytokines, such as ACTA2, FBLN1, TAGLN, etc., remodeling the tumor extracellular matrix, thereby leading to tumor progression." (PMID 38755647, 2024). "Here, we show that GSCs express high levels of TAGLN relative to the other tumor cells, and TAGLN informs poor prognosis for GBM patients." (PMID 38087889, 2024). "The expression of fibrotic genes EGR1, JUND, KLF2 and TAGLN also decreases in tumour samples (PH4 module)." (PMID 38157373, 2023). "RNA transcriptomic analysis showed a gene significantly associated with the low cytoplasmic S100A2 group (AKT3, TAGLN, MYLK, FGD6 and ETFDH), which correlated with tumour development and progression." (PMID 37476187, 2023). "Contrarily, TAGLN expression is commonly downregulated in tumor cells in comparison with the cells of healthy tissue." (PMID 37047799, 2023). "Taken together, these findings suggest that TAGLN activates fibroblasts and, in turn, induces their pro-tumor phenotype." (PMID 36990991, 2023). "Here, we show that TAGLN overexpression can promote tumor spreading and tumor cell migration/invasion through the release of pro-inflammatory cytokines, namely interleukin-6 (IL-6), via NF-κB signaling pathway activation." (PMID 36990991, 2023). "Analysis of paired samples with both FFPE tissues and fresh frozen tumors showed that transcript levels of ACTA2, TPM2, CALD1, and TAGLN were significantly and positively correlated with the stromal percentage of the tumor." (PMID 37296997, 2023). "Another miR, miR-22-3p, mediated tumor vessel abnormalization by suppressing transgelin, thus promoting tumor budding and BC progression in vivo." (PMID 37108371, 2023). "Tumor microarrays (TMAs) revealed that increased stromal TAGLN levels correlates with more lymphatic metastasis of tumor cells." (PMID 36990991, 2023). "Combining these results, we showed that TAGLN exists predominantly in fibroblasts from the tumor stroma." (PMID 36990991, 2023). "The loss of stromal CAV1 in turn was accompanied with increased (stromal) TAGLN levels, an observation that was shown to account for a more activated and reactive nature of the respective tumor stroma." (PMID 35155239, 2022). "Spearman’s correlation coefficient displayed that IGFBP4 were significantly correlated with the tumor metastasis (ρ = − 0.843, P < 0.001), enneking stage (ρ = − 0.500, P < 0.001), and TAGLN (ρ = 0.821, P < 0.001)." (PMID 35665757, 2022). "Exosomal miRNA-22-3p targeting transgelin (TAGln) promotes tumour progression and angiogenesis in vivo." (PMID 36096820, 2022). "The protein expression levels of AEBP1, BGN, and TAGLN in tumor tissues were higher than those in normal tissues." (PMID 36523769, 2022). "A group of cells (C5) that did not express EMT signatures, but highly expressed myofibroblast-associated genes such as TAGLN and EGR1 was identified in the tumor cell clusters analysis." (PMID 35087207, 2022). "We found that increased expression of two markers, thrombospondin 2 (THBS2) and transgelin (TAGLN), was associated with poorer OS in MOC after adjustment for age and tumor stage." (PMID 36222710, 2022).
tumor (continued). "The results showed that pathologic grade (P = 0.002), tumor metastasis (P < 0.001), and enneking stage (P < 0.001) were markedly related to the TAGLN." (PMID 35665757, 2022). "The expression of SLC27A2, SFRP2, KRT17 were up-regulated in tumor tissues (p<0.05), the expression of TAGLN was down-regulated (p<0.05), while those of NAT2 remained unchanged (p>0.05), compared with the levels in the corresponding normal tissues." (PMID 36479114, 2022). "Spearman’s correlation test showed that IGFBP4 were significantly correlated with the tumor metastasis (ρ = − 0.843, P < 0.001), enneking stage (ρ = − 0.500, P < 0.001), and TAGLN (ρ = 0.821, P < 0.001)." (PMID 35665757, 2022). "Spearman’s correlation coefficient displayed that pathologic grade (ρ = 0.177, P = 0.041), tumor metastasis (ρ = − 0.677, P < 0.001), and enneking stage (ρ = − 0.600, P < 0.001) were significantly correlated with TAGLN." (PMID 35665757, 2022). "According to the Human Protein Atlas database, we found that the protein expression levels of AEBP1, BGN, and TAGLN in tumor tissues were higher than those in normal tissues." (PMID 36523769, 2022). "In combination with the results of molecular docking, it is a strongly hint that the anti-tumor effect of JS-K is achieved by binding to TAGLN." (PMID 34001947, 2021). "The result of CCK8 assay suggested that the anti-tumor effect of JS-K is significantly weakened when TAGLN is knocked down in the HepG2.2.15 cells." (PMID 34001947, 2021). "It suggested that the anti-tumor effect of JS-K is significantly weakened when TAGLN is knocked down in the HepG2.2.15 cells." (PMID 34001947, 2021). "We observed that silencing TAGLN using shRNA restrained tumor progression and lowered the metastasis rate, suggesting that TAGLN mediated stiffness-regulated OC progression." (PMID 34538264, 2021). "ciRS-7 acts as a tumor promoter by regulating the miR-139-3p/TAGLN axis and activating the PI3K/AKT signaling pathway to promote RCC progression and metastasis." (PMID 34740354, 2021). "First, we explored the expression of TAGLN in 275 tumor and 349 normal tissue from the TCGA/GTEx COAD dataset." (PMID 32393769, 2020). "In this study, we found that COMP regulated tumor cytoskeletal remodeling and promoted mesenchymal transition by interacting directly with TAGLN." (PMID 32754278, 2020). "Transgelin has been shown to be a poor prognostic factor associated with advanced CRC and it also promotes transforming growth factor β (TGF β)-dependent tumor growth and migration." (PMID 32774160, 2020). "Firstly, we suppose that transgelin directly takes part in the cytoskeletal remodeling in the cytoplasm following cancer cells signaling from the tumor microenvironment." (PMID 32774160, 2020). "Forced expression of TAGLN was associated with enhanced CRC cell proliferation, clonogenic growth, cell migration and in vivo tumor formation in immunocompromised mice, while targeted depletion of TAGLN exhibited opposing biological effects." (PMID 32393769, 2020). "The reduction in the expressions of TAGLN are often found in tumor cell lines, and the TAGLN depletion increases actin dynamics and enhances tumorigenic phenotypes of the cells." (PMID 31591355, 2019). "Overexpression of TAGLN was strictly limited to the regulation of the tumor-induced, reactive, myofibroblastic stromal tissue, compartment-specific cell type’s expression in tumoral stroma compared to neoplastic epithelial cells." (PMID 31591355, 2019). "The effect of TAGLN on tumor growth in vivo was evaluated by using xenografts in BALB/cAnN-Foxn1NU mice." (PMID 31591355, 2019). "A prior study has suggested that TAGLN and trangelin-2 act as cancer biomarkers and are differentially expressed in the tumor and stroma cells." (PMID 31591355, 2019). "For example, CPPED1, GPRC5A, and TAGLN, recently reported to have tumor-suppressive function (57, –, 59), were significantly downregulated at both the mRNA and protein level." (PMID 30918060, 2019).